PREX2 (phosphatidylinositol-3,4,5-trisphosphate dependent Rac exchange factor 2)
Diseases named in the same sentence as PREX2 in open-access papers (continued):
Sharing a sentence is not in itself a finding about the gene and the disease.
lung carcinoma (5 papers, 2019 to 2025). "We isolated several PREX2 mutations that exist in lung cancer through database screening, including P674Q, Q690L, T936A, S926Y, D1256N as well as C243F, which is located in DH-PH domain of PREX2 and exists in NSCLC cell line H1299." (PMID 40365293, 2025). "Phosphatidylinositol-3,4,5-triphosphate-dependent RAC exchange factor-2 (PREX2) is highly expressed in multiple cancer types and poses high mutation frequency in lung cancer." (PMID 40365293, 2025). "Skin and lung cancers represent the tumors that most frequently bear PREX2 mutations." (PMID 40365293, 2025). "The relatively higher expression of PREX2 in lung cancer tissues and NSCLC cell lines suggests that dysregulation of PREX2 may play a role in NSCLC." (PMID 40365293, 2025). "In lung cancer, PREX2 played an important role in mediating the activation of PI3K/Akt signaling pathway, which might provide the evidence for the higher mutation frequency in MP-LUAD cases." (PMID 36531058, 2022). "To elucidate the expression level of PREX2 in NSCLC, we performed immunohistochemistry (IHC) analysis with 90 paired human lung cancer and matched adjacent tissues." (PMID 40365293, 2025). "Overall, our findings suggested that PREX2 and AHCYL1 played important roles in lung cancer and illustrated a novel regulatory mechanism of PREX2 function by AHCYL1." (PMID 40365293, 2025). "By IHC analysis with 90 paired human lung cancer and matched adjacent tissue arrays, we found that AHCYL1 expression level in tumor tissues was relatively higher than that in matched adjacent tissues and positively correlated with PREX2 expression." (PMID 40365293, 2025). "However, the study of PREX2 in lung cancer, especially NSCLC is few and unclear, thus, the role of PREX2 and the regulatory mechanism of PREX2 in NSCLC is worthy of further investigation." (PMID 40365293, 2025).
pancreatic cancer (4 papers, 2019 to 2023). "PREX2 can reportedly promote cell proliferation, invasion, and migration in pancreatic cancer." (PMID 35453806, 2022).
pancreatic ductal adenocarcinoma (4 papers, 2017 to 2024). An infiltrating adenocarcinoma that arises from the epithelial cells of the pancreas. "In another study which recruited 100 pancreatic ductal adenocarcinoma patients, only 10% of the cohort was identified to have PREX2 mutations." (PMID 30796242, 2019).
liver cancer (3 papers, 2022 to 2024). An epithelial or non-epithelial malignant neoplasm that arises from the liver. "In the TCGA liver cancer cohort, cases with PREX2 mutations had significantly shorter OS in comparison to cases without PREX2 mutations." (PMID 35174643, 2022).
non-small cell lung carcinoma (3 papers, 2021 to 2025). A group of at least three distinct histological types of lung cancer, including non-small cell squamous cell carcinoma, adenocarcinoma, and large cell carcinoma. "CELF2-AS1 (CELF2 Antisense RNA 1) (average methylation 80%, p = 0.02) suppresses non-small cell lung carcinoma growth by inhibiting the PREX2-PTEN interaction, which regulates cell proliferation." (PMID 38791918, 2024). "Further evidence can be found in non-small-cell lung cancer, where CELF2 is capable of inhibiting tumor development by antagonizing PREX2 (Phosphatidylinositol-3,4,5-Trisphosphate Dependent Rac Exchange Factor 2)’s oncogenic impact and regulates PI3-K signaling." (PMID 34681716, 2021).
adenoma (2 papers, 2025). A neoplasm arising from the epithelium. "However, tumors from Prex2-KO-urethane mice displayed only a few adenomas, and lungs from this group retained a majority of the normal alveolar architecture." (PMID 40365293, 2025).
glioma (2 papers, 2020 to 2023). A benign or malignant brain and spinal cord tumor that arises from glial cells (astrocytes, oligodendrocytes, ependymal cells). "Genes involved in the PI3K-AKT oncogenic pathway were also identified including known tumor suppressor genes in gliomas such as Pten and Pi3kr1 as well as novel genes including Prex2, and the protein tyrosine phosphatases Ptpro and Ptprj, all with inactivating transposon insertional patterns." (PMID 32727536, 2020).
lung adenocarcinoma (2 papers, 2023 to 2025). A carcinoma that arises from the lung and is characterized by the presence of malignant glandular epithelial cells. "By analyzing the TCGA cohort, we found that PREX2 RNA abundance is correlated with PREX2 copy numbers except in those lung adenocarcinoma (LUAD) patients with high expression of PREX2." (PMID 40365293, 2025).
lung squamous cell carcinoma (2 papers, 2021 to 2025). "The Kaplan-Meier analysis showed that high copy number and high expression of PREX2 in lung squamous cell carcinoma (LUSC) patients had a significantly shorter survival time but not in LUAD patients." (PMID 40365293, 2025).
bacterial pneumonia (1 paper, 2022). Acute infection of the lung parenchyma caused by bacteria (e.g., Streptococcus pneumoniae, Haemophilus influenzae, Chlamydia pneumoniae, Mycoplasma pneumoniae, and Legionella pneumophila). "Prex1–/–/ Prex2–/– mice have a more severe impairment in motor control than Prex2−/−, as well as showing immune-deficiency during bacterial pneumonia." (PMID 36342857, 2022).
brain arteriovenous malformations (1 paper, 2022). "PREX2 is associated with brain arteriovenous malformations that can induce vascular amyloid β deposition, which is a significant risk factor for AD." (PMID 35627223, 2022).
colorectal cancer (1 paper, 2024). A primary or metastatic malignant neoplasm that affects the colon or rectum. "In summary, this study not only identifies PREX2 as a potential biomarker for colorectal cancer radiation therapy response but also offers insights into a novel treatment strategy." (PMID 38609982, 2024). "In summary, our discoveries underscore the pivotal role of PREX2 in colorectal cancer (CRC) radiation resistance, with its influence predominantly channeled through the cGAS/STING/IFN signaling pathway." (PMID 38609982, 2024). "This study establishes, for the first time, a direct correlation between PREX2 expression and the radiation response in colorectal cancer (CRC)." (PMID 38609982, 2024). "To delve deeper into the intricate mechanism of PREX2 in colorectal cancer (CRC) radioresistance, we conducted RNA-seq to unveil and identify pathways influenced by PREX2 in CRC cells." (PMID 38609982, 2024).
Glucose intolerance (1 paper, 2025). Glucose intolerance (GI) can be defined as dysglycemia that comprises both prediabetes and diabetes. "Furthermore, both male and female Prex2–/– mice on high-fat diet (HFD) were protected from developing diet-related glucose intolerance, the males partially and the females fully." (PMID 40764335, 2025).
hepatoblastoma (1 paper, 2021). Hepatoblastoma (HB) is a malignant hepatic tumor and is the most common pediatric liver cancer. "There are also no data on the relationship of mutations in the PREX2 gene with hepatoblastoma; however, it has been shown that in 23.5% of patients with HCC, there is a non-silent somatic mutation of PREX2." (PMID 34884942, 2021).
Insulin resistance (1 paper, 2025). Increased resistance towards insulin, that is, diminished effectiveness of insulin in reducing blood glucose levels. "In contrast, Prex2–/– mice showed bona fide insulin resistance." (PMID 40764335, 2025).
ovarian serous cystadenocarcinoma (1 paper, 2019). A malignant serous cystic epithelial neoplasm arising from the ovary. "Recently using genome-wide methylation data analysis, five-methylation signature (SLC39A14, PREX2, KCNIP2, CORO6, and EFNB1) were reported as novel independent prognostic biomarker for patients with ovarian serous cystadenocarcinoma, which significantly associated with OS of patients." (PMID 31608277, 2019).
prostate carcinoma (1 paper, 2023). A carcinoma that arises from epithelial cells of the prostate gland. "Up-regulation of PREX2 is considered a prognostic factor for poorer outcomes for patients with breast and prostate cancer." (PMID 37048724, 2023).
rectal cancer (1 paper, 2024). A primary or metastatic malignant neoplasm that affects the rectum. "In this study, we found that PREX2 expression was upregulated in radioresistant CRC, both in the array profiling from rectal cancer patients (GSE145037 and GSE150082) and in clinical CRC tissues." (PMID 38609982, 2024).
renal cell carcinoma (1 paper, 2025). "In renal cell carcinoma (RCC), for example, a panel of mRNA markers (CUL9, KMT2D, PBRM1, PREX2, and SETD2) has been identified as a highly accurate classifier, distinguishing RCC from benign renal masses with an AUC of 0.83." (PMID 40149276, 2025).
sarcoma (1 paper, 2017). A usually aggressive malignant neoplasm of the soft tissue or bone. "Up to date, it has been shown that miR-338 respectively targeted proto-oncogenes smoothened (SMO), Phosphatidylinositol-3,4,5-trisphosphate-dependent Rac exchange factor 2 (PREX2a), synovial sarcoma and X breakpoint 2 interacting protein (SSX2IP) respectively in several solid tumors." (PMID 28423738, 2017).
T-cell acute lymphoblastic leukemia (1 paper, 2024). Acute lymphoblastic leukemia of T-cell origin. "Notably, we have reaffirmed the well-established associations between transcription factors TLX1 and TLX3 with T-cell acute lymphoblastic leukemia, as well as HOXA11, PREX2, and RET with AML." (PMID 38769532, 2024).
Tinnitus (1 paper, 2023). Tinnitus is an auditory perception that can be described as the experience of sound, in the ear or in the head, in the absence of external acoustic stimulation. "Further studies are needed to test if there is a relationship between PREX2 expression and adverse VS-specific patient outcomes, such as tinnitus." (PMID 37048724, 2023). "These trends were directionally consistent with the results of the RNA-seq analysis with regard to the lower PREX2 and APLN in VS samples associated with tinnitus." (PMID 37048724, 2023). "The genes that were down-regulated in the tinnitus group, were influenced by more than just an outlier value, and had corresponding FC values of >1 included GFAP (logFC= −3.04), APLNR (−2.95), PREX2 (−1.44), and PLVAP (−1.04; all p < 0.01)." (PMID 37048724, 2023). "For example, there was a trend toward greater staining for KCNQ3, NLRP3, and CD68 and lower staining for PREX2 and APLN in the VS samples associated with tinnitus compared to those without tinnitus." (PMID 37048724, 2023). "A surprising finding from the RNA-seq analysis was that PREX2 expression was lower in VS tissue from patients with tinnitus compared to those without tinnitus, which was directionally validated with real-time RT-qPCR and immunohistochemistry." (PMID 37048724, 2023). "Interestingly, the VS patients with tinnitus in this study had, in addition to lower expression of PREX2, numerically smaller tumors than those without tinnitus." (PMID 37048724, 2023).
trachoma (1 paper, 2018). "NPSR1 interacts with phospholipase C and like both PRKG1 and PREX2 (the best candidate associated gene from the trachoma GWAS) is part of the G protein-mediated cascade of intracellular signalling that centres around the PI3K/Akt pathway of cell cycle regulation." (PMID 29967566, 2018).
tumor (36 papers, 2012 to 2025). "The tumor-promoting effect and high mutation frequency of PREX2 make it an attractive target for cancer therapy." (PMID 40365293, 2025). "The overexpression of PREX2 resulted in a higher rate of tumor growth than the control group, causing a less pronounced reduction in xenograft volume post-IR." (PMID 38609982, 2024). "As a frequently mutated gene in multiple cancers, PREX2 can accelerate tumor proliferation and invasion." (PMID 34885197, 2021). "Although both PREX1 and PREX2 play important roles in tumor growth, the incidence of somatic mutation in PREX2 was much higher than that of PREX14." (PMID 30796242, 2019). "All this work supports the conclusion that the over-expression of PREX2 can increase PI3K-dependent tumor growth, and that mutated PREX2 promotes tumorigenesis by increasing RAC-dependent invasiveness." (PMID 28100393, 2017). "The RAC1-activating guanine nucleotide exchange factor PREX2, which is frequently mutated in cancer and which promotes migration and invasion of various neoplasias is down 44-fold." (PMID 27144453, 2016). "Sequencing of another tumor cohort in the evaluation of PREX2 mutations found a 14% frequency in non-synonymous mutations." (PMID 23372575, 2012). "More potential LM progression-related markers were detected in CSF samples than in tumor samples, including PREX2 mutation (P = 0.014), IGF1R mutation (P = 0.034), AR mutation (P = 0.038), SMARCB1 deletion (P < 0.001), SMAD4 deletion (P = 0.0034), and TGF-beta pathway aberration (P = 0.0038)." (PMID 37131253, 2023). "In our study, the cell growth inhibition phenotype of AHCYL1 knockdown and the enhancement on the GEF activity of PREX2 suggest AHCYL1 possesses the tumor-promoting effect." (PMID 40365293, 2025). "Our data suggest that although inactivation of either Prex2 or Pik3cb has little impact upon tumor initiation or progression, both sensitize to MEK1/2 inhibition." (PMID 39636745, 2025). "Taken together, these results demonstrate that AHCYL1 mediates the tumor-promoting effect of PREX2 by regulating the binding and mutual inhibition between PREX2 and PTEN in NSCLC cells." (PMID 40365293, 2025). "Conversely, PREX2 knockdown further suppressed tumor growth and reduced tumor volume in both C57/B6J and nude mice after radiotherapy." (PMID 38609982, 2024). "The radioresistant role of PREX2 was assessed through in vitro colony formation assay, apoptosis assay, comet assay, and in vivo xenograft tumor models." (PMID 38609982, 2024). "PREX2 plays an important role in regulating RAC activity and also participates in tumor susceptibility and disease progression." (PMID 35453806, 2022). "Next generation sequencing analysis of the postoperative tumor tissue revealed that KRAS copy number was increased and detected SMAD4, RNF43, and PREX2 mutations." (PMID 34888240, 2021). "Mule has been reported as a tumor suppressor in HCC that degrades oncogenic PREX2 proteins via ubiquitination." (PMID 33542213, 2021). "It has been demonstrated that ectopic expression of mutant PREX2 accelerates tumor formation of immortalized human melanocytes in vivo." (PMID 32850962, 2020). "A recent study identified a novel tumorigenic mechanism of dysregulation of phosphatidylinositol 3,4,5-trisphosphate-dependent Rac exchanger 2 protein (PREX2) expression in a tumor environment where GNMT expression is inhibited." (PMID 29416626, 2018). "Kaplan-Meier analysis demonstrated that most of the mice injected with cells expressing wild-type PREX2 or GFP exhibited tumor-free survival for more than ten weeks." (PMID 28100393, 2017). "More recently it has been shown that PTEN can inhibit PREX2, and that this can stop tumor cells invading tissue by preventing the activation of an enzyme called RAC." (PMID 28100393, 2017).
tumor (continued). "Four of the mutations, three truncating variants as well as a point mutant, resulted in a statistically significant decrease in tumor-free survival compared to control melanocytes, expressing wild-type PREX2 (PREX2WT) or green fluorescent protein (GFP)." (PMID 28100394, 2017). "By using these cell lines to create tumor xenografts innude mice, the authors showed that ectopic expression of mutant PREX2 accelerated tumorformation." (PMID 25490935, 2014). "PREX2 level was significantly higher in tumor tissues compared with adjacent tissues." (PMID 40365293, 2025). "Manipulation of PREX2 expression could alter several pivotal cellular activities of tumor cells, such as apoptosis, proliferation, and migration in various cancers 14-19." (PMID 40365293, 2025). "The tumor-promoting effects of AHCYL1 in NSCLC appear to rely heavily on its partnership with PREX2, as AHCYL1 knockdown specifically disrupts PREX2 GEF related signaling pathways in NSCLC but not in normal lung epithelia cell NL20 with low expression of PREX2." (PMID 40365293, 2025). "In these previous studies, PREX2 has been considered as a tumor-promoting gene because of its GEF activity toward Rac GTPase and its inhibition of the tumor suppressor PTEN, a lipid phosphatase that antagonizes PI3K by dephosphorylating PIP3, therefore reducing AKT activation 20-23." (PMID 40365293, 2025). "However, the tumor-specific reliance on the PREX2-AHCYL1 axis, as evidenced by different MEK/ERK and PI3K/AKT signaling response in NL20 and NSCLC cells after AHCYL1 knockdown, suggests a potential therapeutic window." (PMID 40365293, 2025). "One of the strategies targeting PTEN to restrain tumor cell invasion is to inhibit PREX2-catalyzed activation, which suggests that drugs targeting PTEN might need to consider the activity of PREX2." (PMID 38803565, 2024). "In our cohort, the expression of PREX2 was downregulated in tumors as compared to adjacent normal tissues and was negatively associated with methylation beta value, suggesting PREX2 may be a tumor suppressor in ESCC." (PMID 38803565, 2024). "However, wild-type PREX2 can also promote tumor growth by suppressing PTEN activity and increasing PI3K signaling." (PMID 28100393, 2017). "The tumors grew rapidly in the control experiments (the median time for tumor-free survival was one week) and any differences in tumor-free survival for the controls and the mice injected with cells expressing mutated PREX2 were not statistically significant." (PMID 28100393, 2017). "In addition to the nine somatic rearrangements detected near the PREX2 locus, amplification of PREX2 was also identified in the tumor samples." (PMID 23372575, 2012). "Consequently, AHCYL1 intensifies the tumor-promoting effects of PREX2 in NSCLC." (PMID 40365293, 2025). "Therefore, AHCYL1 mediated the tumor-promoting effect of PREX2 in NSCLC cells." (PMID 40365293, 2025). "The tumor suppressor PTEN dephosphorylates phosphatidylinositol-3,4,5-trisphosphate to generate phosphatidylinositol-4,5-diphosphate, antagonizing PREX2 activity and PI3K/AKT signaling." (PMID 39636745, 2025). "At the same time, AHCYL1 releases the mutual inhibition between PREX2 and PTEN, thus leading PTEN facility its tumor suppressor function." (PMID 40365293, 2025). "Silencing of PREX2 inhibited cell growth of NSCLC cells and significantly suppressed tumor growth of NSCLC cell-derived xenografts (CDX)." (PMID 40365293, 2025). "Our analysis identified several genes with recurrent HBV integration, including TERT, MLL4, ADAM12, PREX2, and SCFD2 in tumor tissues." (PMID 34209079, 2021).